TLR3 (toll like receptor 3)
Diseases named in the same sentence as TLR3 in open-access papers (continued):
Sharing a sentence is not in itself a finding about the gene and the disease.
viral infection (continued). "Compound 4a antagonist binds to TLR3/dsRNA to suppress TLR3 activity in gastrointestinal viral infections as well as the expression of downstream TLR3/dsRNA signaling pathways, including TNF-α and IL-1β." (PMID 34659656, 2021). "Excessive levels of cytokines such as IL-6 and IL-1β produced via TLR3 signaling prior to viral infection hinder the induction of protective IFN-γ-producing CD4+ and CD8+ T cell populations." (PMID 34067536, 2021). "In agreement with earlier studies showing an upregulation of TLR3 in response to poly(I·C) or bacterial and viral infection, TLR3 was detected in hNPCs upon ZIKV infection." (PMID 33658344, 2021). "Toll-like receptor 3 (TLR3) activation by viral infections plays a key role in promoting inflammatory immune responses that contribute to pulmonary fibrosis in chronic inflammatory respiratory diseases." (PMID 34512638, 2021). "The endogenous expression of APOL1 is induced under inflammatory conditions, such as viral infections, primarily activating the Toll-like receptor 3 (TLR3) via increased type 1 interferons, which is mimicked in vitro by incubation of cells with poly(I:C)." (PMID 34440683, 2021). "Viral infection can induce epithelial cells to produce TSLP through activating the Toll-like receptor 3- interferon-related factor-3 pathway." (PMID 34131408, 2021). "APOL 1 gene expression can be upregulated by viral infection and inflammatory diseases, which activates Toll-like receptor-3 and triggers cell injury pathways, enhancing kidney damage." (PMID 34057983, 2021). "Many virus infections are sensed by TLR3, including respiratory syncytial virus (RSV), rhinovirus, reovirus, Epstein-Barr virus (EBV), and herpes simplex virus-2 (HSV2)." (PMID 33498715, 2021). "TLR3 is an endosomal TLR that binds to double-stranded RNA (dsRNA), which is produced during the replication of many viruses, and TLR3 signaling is thus important for the immune response to certain viral infections." (PMID 34199501, 2021). "Independently of viral infection, these sensors express pattern recognition receptors (PRRs) that recognize viral pathogens, particularly Toll-like receptor-3 (TLR-3) and RIG-I-like receptors in the case of SARS-CoV-2 infection." (PMID 34673813, 2021). "Toll-like receptor 3 (TLR3) is involved in the pathogenesis of viral infections, including influenza, and is located in the endosomal membrane as the sentinel against viral infection to induce interferons." (PMID 33805888, 2021). "Several studies have dissected the role of TLR3 in virus infection using TLR3−/− mice with some suggesting that TLR3-dependent recognition of virus is like a ‘double edge sword’." (PMID 33498715, 2021). "Polyinosinic polycytidylic acid (poly IC) is a synthetic double-stranded RNA that, when administered experimentally, mimics a viral infection by activation of Toll-like receptor 3 (TLR3)." (PMID 34421684, 2021). "In previous work, we showed that the therapeutic effect of IRE can be improved when combined with simultaneous intratumoral administration of Poly-ICLC, a TLR3 agonist that mimics a viral infection and activates a strong innate immunity." (PMID 33575350, 2021). "After entry of SARS-CoV-2, multiple pattern recognition receptors (PRRs) including Toll-like receptor 3 (TLR3), TLR7, retinoic acid-inducible gene 1 (RIG-I), and melanoma differentiation-associated gene 5 (MDA5) sense viral infection." (PMID 34069359, 2021). "Treatment of susceptible mice with poly IC, a ligand of TLR3, prior to TMEV infection exacerbates disease development, whereas this treatment after viral infection decreases the disease development." (PMID 34067536, 2021). "In fact, ssRNA and dsRNA viruses are detectable by TLR7/8 and TLR3, which produce antiviral immune responses by detecting viral infection, activating signaling pathways, and inducing the production of antiviral cytokines and chemokines." (PMID 34659656, 2021).
viral infection (continued). "This statement is consistent with the positive effect of the exogenous dsRNA addition on the elevation of surface TLR3 expression as well as increasing of TLR3 expression on the cell membrane after viral infection." (PMID 33597952, 2020). "This adds on to previously established roles of SARM1 in innate immune response such as negative regulation of toll-like receptor (TLR3) signaling and induction of neuronal apoptosis in response to viral infection." (PMID 32069324, 2020). "The first stimulus was polyinosinic:polycytidylic acid (poly I:C), which is a synthetic analogue of double-stranded RNA (dsRNA), and is usually employed to simulate viral infection via the TLR3/RIG-I (retinoic acid-inducible gene I) agonist." (PMID 32094377, 2020). "IL-10 induced by L. rhamnosus CRL1505 administration is able to attenuate the expression of TF in inflammatory macrophages recruited in response to TLR3 activation of viral infection." (PMID 32670091, 2020). "Poly (I:C), structurally similar to double-stranded RNA, is an immune activator that is used to mimic viral infection, and it is known to interact with TLR3, which is expressed on the cell membrane of B cells, macrophages and dendritic cells." (PMID 32299355, 2020). "On the contrary, studies have provided evidence regarding the protection provided by the TLR3 and MyD88-dependent signaling pathways against viral infections." (PMID 32824595, 2020). "It has been suggested that TLR3 senses viral dsRNA taken up through endocytosis and contributes to defending the host against viral infection by regulating the expression of a range of cytokines." (PMID 32873759, 2020). "In the relationship between TLR3 and skin color, multiple reports demonstrated the involvement of viral infections and vitiligo development." (PMID 33371432, 2020). "That said, there is a consistent observation in this study that early sensors of virus infection (TLR3/7) are downplayed at early time of infection as are IFN-ß and Mx responses, concomitant with high virus titers." (PMID 33230226, 2020). "TLR3 has a complex role in viral infections since it was reported that this PRR mediated both beneficial and detrimental effects during the course of viral infections such as IFV, RSV, SARS-CoV, or MERS-CoV." (PMID 32670091, 2020). "Studies with anti-TLR3 mAbs have shown that fibroblast TLR3 acts on the cell surface to detect viral infections, and endosome maturation is required to evoke TLR3 signaling intracellularly." (PMID 33371432, 2020). "Poly(I:C), a structural analog of dsRNA, binds to toll-like receptor 3 (TLR3) and it has been widely used as an immuno-stimulant in humans and mice against viral diseases based on its ability to enhance innate and adaptive immunity." (PMID 32922394, 2020). "TRIF has been shown to form a complex with TBK-1, a protein kinase that has been reported to directly phosphorylate IRF-3 and IRF-7 in response to viral infection or TLR3 and TLR4 stimulation based on in vitro kinase assays." (PMID 32373120, 2020). "Polyinosinic:polycytidylic acid (pIC) mimics viral infections through binding to pattern recognition receptors (e.g. TLR-3)." (PMID 32641167, 2020). "This allows us to believe that MC stimulation via TLR3 leads to the synthesis of multiple potent mediators entailing the development of inflammation, which is a crucial defensive mechanism during viral infections." (PMID 32185237, 2020). "This is very likely due to the acidification which supports TLR3 activation, and because extracellularly present dsRNA, e.g., released from dead cells following viral infection, undergoes endocytosis." (PMID 33597952, 2020). "HMOX1 is further involved in interferon regulation following stimulation of the innate immune receptors TLR3 and TLR4, and has been implicated in various viral infections." (PMID 33163005, 2020). "LRRFIP1 rapidly colocalises with viruses and interacts transiently with viral sensing Toll-like receptor 3 (TLR3) following viral infection." (PMID 33330501, 2020).
viral infection (continued). "Together, TLR3 agonists hold strong promise, especially in protection against viral infections and for vaccine adjuvant strategies." (PMID 33679711, 2020). "TLR3 acts as a sensor of viral infection and activates downstream innate immunity-related signaling pathways." (PMID 33274246, 2020). "Because TLR3 triggers a strong immune response against viral infection, it is considered a promising drug target for the development of effective vaccine adjuvants." (PMID 32325904, 2020). "This was necessary as TLR3 acts as a sensor of viral infection and activates downstream innate immunity-related signaling pathways." (PMID 33274246, 2020). "OPTN gene expression is regulated through NF-κB signalling and increases upon TLR3 activation by poly(I:C) or viral infection." (PMID 32376785, 2020). "TLR3, which is responsible for the recognition of double-stranded RNA (dsRNA), plays a crucial role in various viral infections of the nervous system." (PMID 32244328, 2020). "Specifically, a primary endpoint of TLR3 activation is the production of interferon-beta, which is necessary to combat viral infections." (PMID 30987646, 2019). "It has been shown that TLR3 or TLR7 sense viral infection in the gut and trigger the production of IFN-β that dampens DSS-induced experimental colitis." (PMID 31130960, 2019). "Expression of those receptors sensitizes endothelial cells to the action of several Gram-negative (Tlr4) and positive (Tlr2) bacteria along with several viral infections (Tlr3)." (PMID 32038494, 2019). "In a Saudi Arabian population, the TLR3 rs78726532 SNP was strongly associated with Hepatitis B (HBV) and Hepatitis C (HCV) virus infections when compared to that in healthy control subjects." (PMID 31574965, 2019). "The homodimeric TLR3 generates signals for the production of IFNs in a TRIF-dependent manner after TLR3 is activated by viral infections (double-stranded RNA)." (PMID 31480568, 2019). "This treatment revealed that even though these are M2-type macrophages, their inflammatory responses were induced through TLR3, suggesting an important role of these cells in controlling viral infections." (PMID 31357391, 2019). "Summarized, our data strongly point towards TLR3 and TLR7 as initiator of inflammation in RE, possibly underlying a viral infection or a post-infectious autoimmune encephalitis." (PMID 30663001, 2019). "A missense mutation (F303S) of the TLR3 gene was found in one out of three patients developing IAV-associated encephalopathy (IAE), a neurological consequence of severe viral infection." (PMID 31574965, 2019). "Hofbauer cells are generally considered to be inefficient at controlling viral infections, even though they express TLR3 which recognizes double-stranded viral RNA." (PMID 31357391, 2019). "The nucleotide-sensing TLR3 is activated by double-stranded viral RNA, which is a sign of viral infection." (PMID 31428138, 2019). "The transcription of type I and type III IFN is also mediated by IFN regulatory factors (IRF3, IRF7), and toll like receptor 3 (TLR3) in response to virus infection." (PMID 31652893, 2019). "This study needs to describe TLR3 at the molecular level in the process of re virus infection and reproduction mechanism, and special emphasis on the condition of KRAS‐mutant CRC, in search of a better method for the treatment of CRC with KRAS mutations." (PMID 29658188, 2018). "Classically, TLR3 is known to initiate a protective immune response against viral infections through the induction of Type I interferons." (PMID 29449840, 2018). "For example, the activation of Toll-like receptor 3 (TLR3) during viral infection leads to the downregulation of DISC1 through myeloid differentiation primary response gene 88 (MYD88) and subsequently impairs dendritic arborization and neuronal development." (PMID 30285728, 2018). "TLR3 recognizes double-stranded viral RNAs, such as the overlapping transcripts generated during viral infection." (PMID 30075008, 2018).
viral infection (continued). "The results of our group, which demonstrate the capacity of immunobiotic strains to beneficially modulate Toll-like receptor 3-triggered immune responses in bovine IECs and improve the resistance to viral infections, are highlighted." (PMID 29599767, 2018). "We therefore chose to trigger TLR3 with poly(I:C), which can be equally sensed by all donors, to simulate a viral infection in LNSCs after which we compared the response between healthy, RA-risk and RA donors." (PMID 29379035, 2018). "Viral dsRNA can stimulate an innate response through TLR3 signaling and, interestingly, the immune activity elicited by TLR3 agonists has been shown to provide protection from different viral infections, among which certain HIV strains." (PMID 30250470, 2018). "TLR3 is an endosomally located TLR that recognizes nucleic acids, specifically, dsRNA, which is associated with viral infection." (PMID 29862343, 2018). "Since TLR3 recognizes double-stranded (ds)RNA, which is the nuclear material of many viruses our data suggest that inhibition of epithelial cell regeneration may be an important mechanism associated with injury of epithelial cells observed during viral infection in the airways of asthma patients." (PMID 30127243, 2018). "The results of in vivo studies in mammalian hosts suggest that activation of TLR3 signaling pathway by its ligand, dsRNA, provides protection against a number of viral infections." (PMID 29530062, 2018). "These cells sense rotavirus dsRNA through PRRs such as TLR3 and activate cellular signaling cascades to react to viral infection." (PMID 30319634, 2018). "It has been well established that the unregulated activation of TLR3 is capable to mediate detrimental inflammatory responses in the intestine, thus contributing to the tissue damage induced by viral infections." (PMID 29599767, 2018). "Viral infections emerge as important events in the etiology of CNS damage, and it was reported that dsRNA/TLR3-activated astrocytes initiate a battery of rapid innate immune responses." (PMID 30505285, 2018). "The results of our group, which demonstrate the capacity of immunobiotic strains to advantageously modulate Toll-like receptor (TLR)-3-triggered immune responses in bovine IECs and improve the resistance to viral infections, are particularly highlighted." (PMID 29599767, 2018). "TLR3 is an endosomal TLR that recognizes double-stranded RNA (dsRNA), a molecular pattern associated with viral infection." (PMID 30886985, 2018). "These cells express endogenous TLR3 and other viral nucleic acid sensors to sense viral nucleic acids during viral infection, thereby triggering type I IFN antiviral responses." (PMID 30563052, 2018). "Chloroquine inhibits TLR3 signalling, which is an important pathway in the response to viral infections, and antigen presentation on MHC class II molecules." (PMID 29772762, 2018). "The propagated importance of pDC for early sensing of viral infection is supported by the high transcription rate of TLR3, TLR7, and TLR9 found in bovine pDC." (PMID 30425716, 2018). "During viral infection, TLR3 located in endolysosomal compartments responds to the presence of double-stranded (ds) RNA, which is usually produced as viruses replicate their genomes." (PMID 29084253, 2017). "TLR3 is thought to be a major mediator of the cellular response to viral infection, because it responds to dsRNA, a common by-product of viral replication." (PMID 28198368, 2017). "Like type I IFNs, type III IFNs are induced in viral infection by the PRR RIG-I as well as TLR3 and TLR9 and rely on the activation of the same transcriptional activators, including IRF3, IRF7, and NFκB." (PMID 28382038, 2017). "TLR3 has been shown to be dispensable or even harmful in several viral infections, such as infection with reovirus, influenza A, rabies virus, and West Nile virus (WNV)." (PMID 28973047, 2017).
viral infection (continued). "TLR-3 is known to play a key role in the host response to virus infection by recognizing virus-derived dsRNA in intracellular vesicles to induce the production of IFN, whereas TLR-4 recognizes viral structural proteins on the plasma membrane." (PMID 29312337, 2017). "We determined the genotype distribution of single-nucleotide polymorphisms (SNPs) within the TLR3 and TLR7 genes in children with HCMV infection and the relationship between TLR polymorphisms and viral infection." (PMID 28046022, 2017). "Viral infections induce a characteristic activation of immune response, e.g., TLR3, 4, 7, 8, 9 in the endosome and their downstream targets, especially MyD88." (PMID 28861088, 2017). "When viral infection occurs, viral recognition receptors, such as Toll-like receptor 3 (TLR3) expressed on BECs, are activated to produce inflammatory cytokines and chemokines, including CXCL10." (PMID 28775743, 2017). "Whilst TLR3 expression was reduced approximate 70%, the viral infection-induced TGF-β expression and GC impairment were prevented." (PMID 28046097, 2017). "A20 knock down results in enhanced IRF3-dependent transcription triggered by the stimulation of TLR3 or virus infection." (PMID 28210256, 2017). "We demonstrate that these TLRs as well as the endogenous receptor TLR3 are up-regulated at the time of TRP-up-regulation by virus infection dependent on cell type." (PMID 28187208, 2017). "The ligand of TLR3 is double-stranded RNA (dsRNA), which has been well-studied in the field of viral infection." (PMID 28487699, 2017). "We used poly I:C as an adjuvant, which acts as dsRNA recognized by TLR3 and thus mimics viral infection." (PMID 28381295, 2017). "Increasing evidence suggests that the mutation that leads to the replacement of the leucine (L) residue in amino acid position 412 by a phenylalanine (F) residue (L412F) in the TLR3 ectodomain plays an important role in viral infection." (PMID 28046022, 2017). "Albeit a role of TLR3 in NK cells during viral infections is still elusive, yellow fever vaccination was able to enhance detection of TLR3 and TLR9 in NK cells early after vaccination, suggesting its role as an activation marker for NK cells." (PMID 29038620, 2017). "The results point to the signaling route involving TLR3, MIF, and TNFα being active in TBE virus infection and contributing to the risk of an overt neuroinvasive disease." (PMID 28646884, 2017). "Reporter assays have also linked missense SNPs that are located within TLR2 and TLR5 to a differential reactivity to Salmonella enterica and within TLR3 to different responses to stimulation by poly(A:C), a synthetic acid that emulates viral infection." (PMID 27036198, 2016). "Viral infection and dsRNA have been shown to increase the amount of extracellular ATP and the production of mucin in airways via TLR3." (PMID 27677339, 2016). "Genes such as Toll-like receptor-3 (TLR3), which participate in recognizing conserved foreign molecules and mounting the first line of defence against viral infections, are promising functional candidates in autoimmune conditions." (PMID 26318769, 2016). "Viral infection, as well as type I IFNs or PolyI:C, are known to upregulate TLR3 expression (52, –, 55)." (PMID 26956584, 2016). "Poly I:C, a synthetic double-stranded RNA, which acts as a ligand of TLR3 receptor (Toll-like receptor 3), has been used as a template to reproduce the acute phase of viral infection." (PMID 28003864, 2016). "Instead, they participate in several functions, including energy metabolism, ion exchange, and glutamate homeostasis, as well as acting as sentinels for viral infection via their expression of the Toll-like receptor 3 (TLR3)." (PMID 26491149, 2016). "There are additional reports suggesting a necessary RIG-1 and TLR-3 interaction to surge innate immunity in response of viral infections." (PMID 27555815, 2016).